WRN (WRN RecQ like helicase)
Diseases named in the same sentence as WRN in open-access papers (continued):
Sharing a sentence is not in itself a finding about the gene and the disease.
Werner syndrome (continued). "Werner Syndrome (WS) and Bloom Syndrome (BS) are disorders of DNA damage repair caused by biallelic disruption of the WRN or BLM DNA helicases respectively." (PMID 32367056, 2020). "There is a subgroup of patients classified as atypical Werner syndrome (AWS), which is used to describe individuals with a clinical diagnosis of WS but a lack an identifiable WRN mutation." (PMID 33194896, 2020). "WS is caused by mutations in a single gene located on chromosome 8, which encodes a nuclear protein termed Werner syndrome protein (WRN)." (PMID 33054770, 2020). "Interestingly, SIRT1-mediated homologous recombination may require WRN, a helicase and exonuclease mutated in the premature ageing Werner syndrome." (PMID 30666570, 2019). "Mutations in Werner syndrome are almost exclusively truncating nonsense, splicing or frameshift mutations affecting WRN nuclear localization, suggesting that concomitant loss of WRN helicase and exonuclease function might be required for the onset of Werner syndrome." (PMID 30910006, 2019). "Werner syndrome (WS) is a rare, autosomal recessive disorder characterized by the appearance of premature aging caused by deficiency of Werner protein (WRN)." (PMID 32010626, 2019). "Patients with Werner Syndrome (WS), exhibit premature aging phenotypes such as gray hair, osteoporosis, diabetes and cancer due to loss-of-function mutations of the WRN gene, which is involved in DNA repair and telomere maintenance." (PMID 31380368, 2019). "Replication stress resulting from WRN mutation may itself drive cellular senescence by triggering a DNA damage response and highly premature senescence is characteristic of Werner syndrome patient-derived cells." (PMID 30666570, 2019). "Defects in the WRN helicase are linked to a form of progeria associated with accelerated aging phenotypes termed Werner syndrome (WS)." (PMID 31210839, 2019). "Most WS cases have been linked to mutations in a single gene, the Werner syndrome gene (WRN), which is located on chromosome 8." (PMID 30400178, 2018). "In particular, we identify two KBMs in the exonuclease/helicase mutated in Werner syndrome (WRN) and show that these motifs are employed by WRN to accelerate chromosomal DSB repair, defining the functional importance of these motifs in vitro and in cells." (PMID 27063109, 2016). "Because the “Werner syndrome ATP-dependent helicase” encoded by the WRN gene plays important roles in both cellular proliferation and DNA repair, we hypothesized that inhibition of WRN activity could be used as a new strategy to target ATLL cells." (PMID 27829440, 2016). "Werner syndrome (WS) is an accelerated ageing disorder with genomic instability caused by WRN protein deficiency." (PMID 27922005, 2016). "Although we could not find any prior literature on the role of RNA helicases in tissue aging, the same cannot be said for DNA helicases: e.g. WRN, which is a member of the RecQ helicase family, is implicated in Werner's syndrome, which is a recessively inherited progeria." (PMID 26000617, 2015). "Werner syndrome (WS) is a premature aging disorder caused by mutations in a RecQ-family DNA helicase, WRN." (PMID 26447695, 2015). "Werner syndrome (WS) is a segmental progeroid syndrome caused by mutations in WRN, encoding a RecQ helicase/endonuclease." (PMID 24308646, 2014). "Mutations in the WRN gene results in the development of Werner syndrome (WS), a rare autosomal recessive disorder characterized by premature ageing and genome instability." (PMID 24626809, 2014). "Werner syndrome (WS) is an autosomal recessive premature aging syndrome due to biallelic inactivating mutations in WRN, encoding a RecQ DNA helicase/exonuclease involved in DNA replication and repair." (PMID 23849162, 2013). "Our International Registry of Werner syndrome has accumulated several dozen cases of “atypical” WS (AWS) – cases submitted by clinicians to us as examples of WS, but lack WRN mutations and have normal levels of the WRN protein." (PMID 23847654, 2013).
Werner syndrome (continued). "Werner syndrome (WS) is associated with rapid acceleration of aging, and is caused by mutations in the RecQ family DNA helicase gene, WRN." (PMID 20062519, 2010). "Loss of the WRN helicase/exonuclease results in Werner syndrome (WS), which is characterized by features of premature aging and cancer predisposition." (PMID 20585393, 2010). "Loss of function mutations in WRN cause progeroid features in humans, a condition known as Werner Syndrome (WS)." (PMID 19554081, 2009). "Werner syndrome (WS) is caused by the inheritance of two copies of null mutations in the WRN locus located at chromosome 8." (PMID 18312663, 2008). "Werner syndrome (WS), caused by mutations in the RecQ helicase WERNER (WRN) gene, is a classical accelerated aging disease with patients suffering from several metabolic dysfunctions without a cure." (PMID 40179319, 2025). "Drosophila WRNexo (CG7670) has been identified as an ortholog of human WRN exonuclease for modeling Werner syndrome." (PMID 40261911, 2025). "WRN deficiency is a known cause of adult progeria (Werner syndrome), and as such, it has been extensively studied in cultured cells derived from Werner syndrome patients and in model organisms with WRN depletion." (PMID 40261911, 2025). "Over the past decade, studies of WRN have focused on its role in Werner syndrome, while little is known about its function in natural aging." (PMID 40261911, 2025). "Unlike human WRN, which has both exonuclease and helicase activities, Drosophila WRN possesses only exonuclease activity and is therefore named Werner syndrome exonuclease (WRNexo)." (PMID 40261911, 2025). "The WRN gene encodes the WRN helicase and is usually mutated in Werner syndrome (WS)." (PMID 40728512, 2025). "Werner syndrome ATP-dependent helicase (WRN) is a member of the RecQ family of DNA helicases that uniquely possesses both helicase and 3′ to 5′ exonuclease activities." (PMID 40573290, 2025). "Werner syndrome (WS) was first described in 1904 by German physician Otto Werner as a rare autosomal recessive disorder caused by mutations in the WRN gene notable for its hallmark feature of premature aging, in association with other comorbidities, including malignancies." (PMID 39958080, 2025). "A similar RecQ helicase, WRN (Werner syndrome), is also important for telomere replication as its depletion results in large telomeric deletions." (PMID 39483338, 2024). "Werner syndrome of premature aging, WS, is caused by loss of function mutations in the RECQ helicase/exonuclease WRN." (PMID 39422615, 2024). "Werner syndrome (WS) is an autosomal recessive disease caused by loss of function of WRN." (PMID 39125869, 2024). "The hunt for the WRN Werner syndrome gene was all the more pressing in light of the seminal publication in 1995 of the cloning of the BS-associated gene BLM that was immediately identified as a member of the human RECQ gene family." (PMID 38994931, 2024). "Results showed that Werner Syndrome ATP-dependent helicase (WRN) was a top hit and a promising target for microsatellite instability tumors." (PMID 38725484, 2024). "Werner syndrome is a germline WRN (RECQL2) inactivation located at chromosome 8p12, found most commonly in Japan, and usually diagnosed in the fourth decade of life." (PMID 37894411, 2023). "Under most circumstances, the pleiotropic genes responsible for POI cause syndromic POI, which manifests with highly variable somatic abnormalities in addition to reproductive phenotypes, such as BLM for Bloom syndrome and WRN for Werner syndrome." (PMID 36793102, 2023). "For instance, through the DepMap database search, Werner syndrome ATP-dependent helicase (WRN DNA helicase) was identified as a synthetic lethal gene in different cancer cells that harbor mutations in DNA mismatch repair." (PMID 37908590, 2023).
Werner syndrome (continued). "Building upon the associations of BLM/RECQ2 and WRN/RECQ3 with Bloom’s syndrome and Werner’s syndrome, investigations were initiated to uncover hereditary diseases linked to RECQ1, RECQ4, and RECQ5." (PMID 37626846, 2023). "The Werner syndrome ATP-dependent helicase (WRN) is a RecQ enzyme involved in the maintenance of genome integrity." (PMID 37130431, 2023). "RecQL1 is the E. coli RecQ ortholog, RecQL2 and RecQL3 are the BLM and WRN genes responsible for Bloom and Werner syndromes, respectively." (PMID 36292687, 2022). "Mutations in the WRN gene give rise to the Werner syndrome (WS)." (PMID 35163467, 2022). "Werner syndrome ATP‐dependent helicase (WRN) is a member of the RECQ family of DNA helicases, involved in unwinding of double‐stranded DNA for replication and repair processes." (PMID 35567571, 2022). "RecQL2 and RecQL3 are the BLM and WRN genes responsible for Bloom and Werner syndromes, respectively." (PMID 36292687, 2022). "There are five members of RecQ, which are RECQL (also called RECQL1), BLM (Bloom’s syndrome gene), WRN (Werner’s syndrome gene), RECQL4, and RECQL5 with unique biochemical functions." (PMID 35267530, 2022). "Other noteworthy findings of our study include a possible interaction between a newly identified locus, RAD52 and WRN, the Werner syndrome ATP‐dependent helicase." (PMID 34704651, 2021). "It is thought that Werner syndrome symptoms are largely due to WRN’s crucial function during telomere maintenance." (PMID 34946868, 2021). "For example, WRN, BLM, and RECQ4 are closely associated with the Werner syndrome, Bloom syndrome, and Rothmund Thomson syndrome, respectively, for which there are currently no effective therapies." (PMID 33828983, 2021). "In a comparison of individuals starting to show aging, Werner syndrome (WS) is characterized by the adult-onset of the progeroid syndrome, and it is caused by mutations in the WRN gene, which encodes a multifunctional protein with 3′-5′ helicase and 3′-5′ exonuclease functions." (PMID 34943966, 2021). "Mutations in WRN, BLM, and RecQL4 cause Werner syndrome (WS), Bloom syndrome (BS), and Rothmud-Thomson syndrome (RTS), respectively, which are associated with premature aging, cancer predisposition, and chromosome abnormalities." (PMID 33266355, 2020). "Werner syndrome (WS) is a cancer-prone disease caused by deficiency of Werner protein (WRN)." (PMID 30657978, 2019). "The Werner syndrome ATP-dependent helicase (WRN) is a well-known RecQ-like helicase that plays a major role in genome stability, particularly during DNA replication and telomere metabolism." (PMID 30654820, 2019). "Instead, a different study also focused on human premature aging used a stem cell model generated by knocking out exons of the WRN gene in wild-type embryonic stem cell lines and subsequently differentiated to MSCs to mimic the Werner syndrome (WS)." (PMID 28102490, 2017). "In addition, Werner Syndrome RecQ Like Helicase (WRN) has a key part in recombination, transcription, repair, and DNA replication, as well as telomere maintenance, suggesting that the prominent inducer for Werner syndrome pathogenesis associated with genomic instability." (PMID 28030852, 2017). "Werner syndrome (WS) is a rare inheritable progeroid syndrome caused by a mutation in the WRN gene." (PMID 28738022, 2017). "Rqh1 is a RecQ family 3’-5’ DNA helicase that is orthologous to human WRN (Werner syndrome) and BLM (Bloom syndrome) DNA helicases, and S. cerevisiae Sgs1 DNA helicase." (PMID 28922417, 2017). "This protein used its nuclease activity to degrade reversed fork and restarted replication in cooperation with ATPase activity of the Werner syndrome ATP-dependent helicase (WRN)." (PMID 28718810, 2017). "Werner Syndrome (WS) is a rare, autosomal recessive human disorder resulting from mutations in the WRN gene, which encodes the RECQ3 DNA helicase." (PMID 27136566, 2016).
Werner syndrome (continued). "Mutations in three of the five human RECQ helicases, BLM, WRN and RECQ4, lead to genetic disorders as Bloom, Rothmund-Thompson and Werner’s syndromes that are associated with cancer predisposition, premature ageing and developmental abnormalities." (PMID 26877874, 2016). "WRN, the protein defective in Werner syndrome, plays critical roles in preventing replication stress, chromosome instability, and tumorigenesis." (PMID 26695548, 2016). "Premature ageing syndrome genes ATM (ataxia-telangiectasia), DKC (dyskeratosis congenita) and WRN (werner syndrome) all exhibited lower transcript abundance in older individuals, concordant with loss-of-function alterations in disease-related mutations." (PMID 26490707, 2015). "Taken together, our results suggest a pathophysiological link between WRN protein expression in Müller cells and the development of refractory CME associated with Werner syndrome." (PMID 24620826, 2014). "Mutations in WRN cause Werner syndrome (WS), an autosomal recessive disease; it may prevent the helicase from entering the cell nucleus, typically leading to premature aging symptoms and earlier onset of cancer." (PMID 25018888, 2014). "Genetic analyses detected compound heterozygosity, Mut4 and Mut11, in the WRN gene and the individual was diagnosed with Werner syndrome." (PMID 24620826, 2014). "A problem with Werner syndrome patients' cells is that, because of the inability for the WRN helicase to function normally, a buildup of insoluble proteins aggregates occurs with increasing oxidative damage to the cell." (PMID 25018888, 2014). "Mutations in WRN underlie Werner syndrome (WS), which is a rare autosomal recessive disease." (PMID 23443494, 2013). "Werner syndrome (WS, OMIM #277700) is an autosomal recessive disease caused by loss of function mutations in the WRN gene." (PMID 23573208, 2013). "The progeroid human Werner syndrome presents a useful model system to study the biology of ageing by investigating the role(s) of the protein WRN, the function of which is lost in WS." (PMID 22562358, 2013). "The WRN gene is a DNA helicase and exonuclease that plays a deterministic role in DNA repair and another progeroid syndrome, Werner's Syndrome." (PMID 22279548, 2012). "Sgs1 is related to human RecQ helicases WRN, defective in the premature aging disorder Werner's syndrome, and BLM, defective in the cancer-prone disorder Blooms' syndrome." (PMID 22319457, 2012). "Germline mutations in the WRN gene cause an autosomal recessive disorder, Werner syndrome (WS)." (PMID 22545052, 2012). "Complete functional inactivation of the WRN protein in human leads to the premature aging disorder Werner syndrome." (PMID 21559242, 2011). "Several studies have suggested that telomere dysfunction and chromosomal aberrations are associated with the aging phenotype associated with Werner syndrome (WS), a rare human premature aging disease that is caused by mutations in the gene encoding the RecQ helicase WRN." (PMID 20052289, 2010). "The Werner protein (WRN), defective in the premature aging disorder Werner syndrome, participates in a number of DNA metabolic processes, and we have been interested in the possible regulation of its function in DNA repair by post-translational modifications." (PMID 18398454, 2008). "Three of the five human RecQ genes, designated BLM, WRN and RECQ4, have been genetically linked to the autosomal recessive diseases Bloom Syndrome (BS), Werner Syndrome (WS) and Rothmund-Thomson Syndrome (RTS), respectively." (PMID 18074021, 2007). "Checkpoint activity was found to be impaired in cells from four Werner Syndrome patients and was restored when WRN (Werner helicase) was expressed, which indicated a role for WRN in the decatenation checkpoint." (PMID 17211475, 2007).
Werner syndrome (continued). "The c.1578del variant in the WRN gene, previously not described in literature in a homozygous state, causes Werner syndrome and is associated with pronounced hallmarks of early senescence in the proband’s fibroblasts." (PMID 40060251, 2024). "The global variance of DNA methylation in HGPS or Werner syndrome is independent of LMNA or WRN mutations, indicating the role of DNA methylation in aging syndrome." (PMID 38355681, 2024). "However, there was an identified variant of unknown significance of the WRN gene, an autosomal recessive gene associated with Werner syndrome (WS)." (PMID 38104125, 2023). "Using state-of-the-art technologies, such as genome, transcriptome, and epigenome analyses, study of the generation of iPS cells from patients with Werner syndrome and the correction of the WRN gene by the CRISPR/Cas9-mediated methods will create new treatments for patients with Werner syndrome." (PMID 37130431, 2023). "Furthermore, they extended the effect of Progerinin to Werner syndrome, a rare progressive genetic disorder that results from a functional defect of the human WRN protein, a member of the RecQ DNA helicase family." (PMID 35205210, 2022). "Werner syndrome (WS; OMIM# 277700) is a rare autosomal recessive, segmental progeroid syndrome caused by homozygous or compound heterozygous loss of function mutations in the WRN gene." (PMID 34201700, 2021). "Kamatlh‐Loeb discovered that the Werner syndrome‐related gene WRN might combine with the p66 subunit of DNA pol δ and further mediate DNA replication and damage repair." (PMID 32432416, 2020). "Werner syndrome (WS; MIM #277700), sometimes termed progeria of adulthood, is a rare autosomal recessive disorder caused by a defective helicase due to homozygous or compound heterozygous mutations in the WS RecQ-like Helicase gene (WRN; MIM #604611)." (PMID 30023403, 2018). "Our findings indicate that homozygous TT individuals who have close to 90% reduction of WRN helicase activity do not present signs or symptoms diagnostic of Werner syndrome in the Mexican population." (PMID 28276523, 2017). "No typical presentation of Werner syndrome was observed because the deleterious WRN mutations are heterozygous in the identified members of this family." (PMID 26241669, 2015). "A pathological link may exist between mutations in the WRN gene and the development of CME in patients with Werner syndrome." (PMID 24620826, 2014). "Interestingly, this module contains the PARP1 (ADPRT) gene, which directly binds to WRN to induce apoptosis upon oxidative stress induced DNA damage and is as such a prime suspect for Werner syndrome, a premature aging disease." (PMID 24119000, 2014). "Some Werner syndrome patients develop type II diabetes mellitus, which may be related to abnormal WRN expression in the pancreas." (PMID 24620826, 2014). "Germline mutations in the human RecQ helicase homologs WRN, BLM and RECQ4 are responsible for the rare genetic disorders of Werner Syndrome, Bloom Syndrome, and Rothmund-Thomson Syndrome, respectively, all of which are characterized by chromosomal instability and predisposition to cancer." (PMID 23650516, 2013). "No evident genotype-phenotype correlations have been reported in Werner syndrome, although proximal truncation of WRN protein could lead to severe phenotypes." (PMID 23849162, 2013). "The homozygous p.Q748X WRN mutation of patient 1 was previously found in a Caucasian man diagnosed with Werner syndrome, but his clinical features were not reported, whereas patient 2 was affected by new WRN mutations." (PMID 23849162, 2013). "Human RecQ homologs include RECQ1, BLM, WRN, RECQ4, and RECQ5β, three of which have been linked to diseases with elevated risk of cancer and growth defects (Bloom Syndrome and Rothmund-Thomson Syndrome) or premature aging (Werner Syndrome)." (PMID 23650516, 2013).